VCAM1 (vascular cell adhesion molecule 1)
Diseases named in the same sentence as VCAM1 in open-access papers (continued):
Sharing a sentence is not in itself a finding about the gene and the disease.
tumor (continued). "We used three promising tumor markers for evaluation of the marker concentration in local fluid: osteopontin (sOPN), splice variant 6 of sCD44 (sCD44-v6) and vascular cell adhesion molecule-1 (sVCAM-1)." (PMID 25185697, 2014). "Genetic changes in the dormant cells, for example loss of metastasis suppressor genes or upregulation of VCAM-1, can stimulate the awakening of dormant tumor cells." (PMID 22699312, 2012). "Interestingly, while ICAM-1 and VCAM-1 were depleted in presence of Bortezomib, authors concluded loss of E-Selectin alone was necessary to reduce adhesion of tumor cells." (PMID 40071851, 2025). "Vascular cell adhesion molecule (VCAM)-1, an immune cell adhesion mediator, is implicated in tumor progression; however, its prognostic and immunomodulatory roles in GC remain unclear." (PMID 40927361, 2025). "VCAM-1 and its receptor integrin α4 are upregulated by tumor-associated LECs." (PMID 41511312, 2025). "Microbubble systems targeted to molecular markers on angiogenic endothelia have been proposed as an intriguing diagnostic platform for detecting and monitoring tumour neovascularisation during cancer, and VCAM-1 serves as a cancer-indicative biomarker for tumour-associated microvessels." (PMID 40095109, 2025). "However, in blood, we observed the same trend again as in tumor where high VCAM-1 and ICAM-1 levels showed a significant association with a low-medium SCS." (PMID 40652770, 2025). "For instance, concentrated regions of aberrant VCAM-1 expression, either on inflamed endothelia or on tumour surfaces, could potentially detect IBD-associated inflammatory conditions or sites of CRC metastasis when screening for colorectal disease." (PMID 40095109, 2025). "Evidence for immune evasion via VCAM-1 expression has been linked to P3 tumor progression." (PMID 38786066, 2024). "Enterotoxin produced by enterotoxigenic E. coli might activate a cGMP-dependent signaling pathway that decreases VEGF and VCAM-1, both associated with angiogenesis and tumor metastasis." (PMID 38139030, 2023). "In this context, upregulation of VCAM-1 and integrin α4 expression in tumor-associated LECs, due to the presence of tumor-derived inflammatory factors, leads to weakened LEC junctions, further contributing to increased lymphatic permeability and cancer cell penetration into LVs." (PMID 37744339, 2023). "We next tested whether the integrin ligands ICAM-1 and VCAM-1 were expressed by tumor-associated myeloid subsets, with a particular interest in macrophages, monocytes, and cDC2s, the myeloid cell types we previously found promote T-ALL survival." (PMID 37805579, 2023). "Since many tumor cells had detached from SpheroidT at this time, we suspected that this reduction in Vcam1 might be associated with tumor cell dissemination." (PMID 36828890, 2023). "Vascular cell adhesion molecule-1 (VCAM-1) is also associated with tumor metastasis." (PMID 37175126, 2023). "A similar mechanism might be activated by IL-8 binding to its receptor in endothelial cells that causes NO signaling, leading to VCAM-1 S-nitrosylation and localization in the plasma membrane to bind circulating tumor cells." (PMID 37773178, 2023). "VCAM-1 is an important protein implicated in tumor cell and leukocyte adhesion to endothelium." (PMID 37773178, 2023). "In addition, blocking FGFR prevents CAF from secreting the vascular cell adhesion molecule 1 (VCAM1), which is closely associated with tumor metastasis and angiogenesis." (PMID 36966334, 2023). "Recent reports have shown that VCAM-1 levels are associated with tumor angiogenesis and metastasis." (PMID 37179352, 2023). "Furthermore, over-expression of VLA-4 was linked to tumor progression in various malignancies when VCAM-1 was also up-regulated." (PMID 36497180, 2022). "The mechanism underlying the association of VCAM-1 with survival may be its relationship with tumor angiogenesis and metastasis." (PMID 35347517, 2022).
tumor (continued). "Moreover, where endothelial VCAM-1 expression was more distant from the tumor mass, these vessels were associated with microscopic disease that would have been undetectable with standard gadolinium contrast-enhanced MRI." (PMID 35312755, 2022). "Furthermore, CCL18/NF-kB/vascular cell adhesion molecule 1 pathway was activated by tumor-associated macrophages, which promotes progression of PDAC." (PMID 35609322, 2022). "Considerable evidence associates VCAM-1 and tumor angiogenesis and metastasis." (PMID 33800796, 2021). "In addition, the progression of PDAC can be promoted by tumor associated macrophages by promoting the Warburg effect through CCL18/NF-kB/VCAM-1 pathway." (PMID 33489882, 2020). "VEGF, ICAM1, and VCAM1 were found to suppress tumor immunity by inhibiting the maturation of dendritic cells, and induce immunosuppressive cells such as regulatory T cells, tumor-associated macrophages, and myeloid-derived suppressor cells." (PMID 33364190, 2020). "The TME further supports effector T cell exclusion from the tumor by hindering the expression of adhesion molecules, such as ICAM-1 and VCAM-1, and inducing the expression of immunosuppressive molecules, such as FasL and PD-L1, at the surface of tumor-associated BECs." (PMID 33096748, 2020). "VCAM-1 expression and tumour presence association has been evidenced." (PMID 32933568, 2020). "VCAM1 is also critical for macrophage-mediated retention of hematopoietic stem cells in the spleen, and there is evidence that these splenic stem cells are a continuous source of tumor associated macrophages throughout tumor progression." (PMID 32298355, 2020). "As expected, a tumor-endothelial cell adhesion assay identified that forced expression of VCAM1 in RKO and Caco-2 cells caused a significant increase in the ability of these cells to adhere to HUVECs, while suppression of VCAM1 impaired the adhesion of LoVo and HCT116 cells." (PMID 32793471, 2020). "Given that angiogenic factors have been shown to cause decrease in ICAM-1 and VCAM-1 expression on tumor associated vessels, targeting angiogenesis could also increase T cell infiltration into tumors." (PMID 31231358, 2019). "Besides on tumor-associated vasculature, aberrant VCAM-1 expression has also been described on many types of tumor cells such as breast, renal and gastric carcinoma cells." (PMID 31231358, 2019). "Also, KSHV infection induced VCAM-1 (3 log2 FC), a vascular endothelial marker that has been linked to tumor angiogenesis and oncogenesis." (PMID 25942495, 2015). "Targeting VCAM1 signaling presents a promising, microenvironment-focused therapeutic strategy, though its clinical application must account for regional and genetic tumor heterogeneity." (PMID 42109665, 2026). "In vitro, AGO1 knockdown in mouse ECs co-cultured with E0771 tumor cells led to higher levels of Cxcl10 and Vcam1 expression, suggesting a pro-inflammatory and leukocyte-recruiting effect." (PMID 42286210, 2026). "The authors demonstrated that their VCAM-1-targeted microbubble formulation was effectively and selectively retained in the tumour vasculature with significantly lower retention in the contralateral leg muscle." (PMID 40095109, 2025). "Tumor-associated vasculature expresses adhesion molecules, such as ICAM-1 and VCAM-1, to facilitate lymphocyte transmigration." (PMID 40475782, 2025). "Endothelial VCAM-1 density obtained by noninvasive imaging correlated with tumor infiltration and response to PDL-1 blockade." (PMID 40071851, 2025). "In liver and colon cancers, elevated expression of ICAM-1, VCAM-1, and MAdCAM-1, ligands to leukocyte-specific integrins, have shown improved T-cells penetration of the tumor and prognosis on patients’ survival." (PMID 40076426, 2025). "VCAM-1 has been reported to be expressed by numerous tumor cell types of pancreatic, breast and gastric cancers." (PMID 40071851, 2025).
tumor (continued). "Because EMT not only enhances motility but also facilitates tumor-endothelial interactions critical for intravasation, we next examined the adhesion molecule vascular cell adhesion molecule-1 (VCAM-1)." (PMID 41300505, 2025). "Our data suggest that the inhibited metastatic phenotype in VCAM1-KO tumor cells involves DPT cells, whereas in immunocompromised NSG mice, CTC-WBC clusters or spontaneous metastasis to the lungs do not decrease." (PMID 40955669, 2025). "Elevated VCAM-1 in ascites highlights its role in tumor-endothelial interactions and metastatic spread, contributing to surgical challenges." (PMID 40652770, 2025). "VCAM1 plays important roles in cell adhesion and intracellular signaling, processes critical for tumor progression and metastasis." (PMID 40227503, 2025). "Together, these data show that Vcam1 on tumor cells is required for optimal CTC-DPT cell cluster formation and spontaneous lung metastasis in mice." (PMID 40955669, 2025). "The neutrophil membrane can recognize tumor cells not only via VCAM-1 expressed on the surface of tumor cells but also through the Fas-Fas ligand interaction." (PMID 40284476, 2025). "Increased expression of endothelial adhesion molecules, intercellular adhesion molecule 1 (ICAM-1), and vascular cell adhesion molecule 1 (VCAM-1) stimulates intra-tumoral lymphocytes infiltration and thus promotes anti-tumour immunity." (PMID 40943273, 2025). "Elevated levels of VCAM-1 and ICAM-1, particularly in tumor tissue, were strongly associated with recurrence, underscoring their potential as biomarkers and therapeutic targets." (PMID 40652770, 2025). "Although ccRCC cancer cells have been reported to be most like injured-like VCAM1+ PTs,20 the presence of multiple cell states within the tumor cell population makes it difficult to determine the founder state." (PMID 39792555, 2025). "On the contrary, other studies have shown that the upregulation of VCAM-1 and its interaction with integrin α4β1 promoted angiogenesis, invasion, and tumor progression in neuroblastoma and gastric cancer." (PMID 40076426, 2025). "The primary ligand for VCAM-1, α4β1 integrin, is expressed on multiple cell types—including monocytes, lymphocytes, and many tumour cell types." (PMID 40095109, 2025). "VCAM-1 mediates distinct tumor-stromal interactions that are unique to lung and bone microenvironments and facilitate metastasis to these sites when aberrantly expressed in breast cancer cells." (PMID 40475782, 2025). "Studies have shown that macrophages can specifically target tumor tissues through the α4β1 integrin, binding to vascular cell adhesion molecule-1 (VCAM-1) on cancer cells." (PMID 40725148, 2025). "In tumor tissue, VCAM-1 and ICAM-1 demonstrated acceptable predictive performance, Area Under the Curve (AUC)=0.600 with cutoff point of 0.553 and AUC=0.664 with cutoff point of 0.475." (PMID 40652770, 2025). "We did not observe any changes in single CTCs or CTC-WBC clusters, suggesting that the reduced metastatic phenotype of Vcam1-KO tumor cells observed in immune competent mice is dependent on the presence of DPT cells." (PMID 40955669, 2025). "Tumor vessels in hypoxic environments are often leaky, disorganized, and deficient in adhesion molecules such as ICAM-1 and VCAM-1, which are necessary for T cell extravasation." (PMID 41048631, 2025). "Immune modulatory molecules, such as CCL2 and CCL5, which recruit tumor-associated macrophages, and adhesion molecules ICAM1 and VCAM1, which facilitate immune cell trafficking, were also included." (PMID 40652770, 2025). "PAK1KO increased the expression of ICAM-1 by 7 times and of VCAM-1 by 10 times in tumour tissues, showing increased density of ICAM-1 and VCAM-1 staining." (PMID 40943273, 2025). "Here, we observed a similar frequency of expression of VCAM-1 on endothelial cells and pericytes on Day 12 of tumor growth (approximately 45% VCAM-1+), with similar levels also seen across tumors and sham controls." (PMID 40244705, 2025).
tumor (continued). "SOX18 upregulates VCAM1 transcription under inflammatory and angiogenic stimuli, suggesting its role in modulating the tumor microenvironment through endothelial activation and immune cell recruitment." (PMID 41373817, 2025). "Studies investigating CRC progression have found a correlation between elevated VCAM-1 expression levels and the extent of tumour development, lymph node involvement, and cancer metastasis." (PMID 40095109, 2025). "Having observed Bevacizumab promotion of TNF-α induction of expression of ICAM-1 and VCAM-1 on the surface of HUVECs above, next we looked at the signs of effective priming of T cells to cross the blood vessel wall into the tumour microenvironment." (PMID 40650058, 2025). "High levels of TNFs and IFN-gamma are present in tumor tissues increasing the expression of VCAM-1 on MSCs and activating their adhesion to endothelial cells, a process necessary for their migration into the tumor microenvironment." (PMID 40573308, 2025). "For the outcome tumor recurrence, both VCAM-1 and ICAM-1 showed good performance in tumor tissue, AUC= 0.838 with cutoff point of 0.746 and AUC=0.835 with cutoff point of 0.708 respectively." (PMID 40652770, 2025). "The macrophage membrane coating enabled the nano-drug to evade immune system clearance, prolong circulation time in the body, and enhance accumulation in tumor tissues by interacting with vascular cell adhesion molecule 1 (VCAM-1) on cancer cells." (PMID 40284476, 2025). "We also analyzed the VCAM-1 regulation patterns in immune cells within the GC tumor microenvironment (TME)." (PMID 40927361, 2025). "A defect in either ICAM-1 or VCAM-1 will result in decreased adhesion of the T-cell to the tumor epithelium, blunting the immunogenic response and resulting in resistance to therapy options." (PMID 40872475, 2025). "Six overlapping hub genes (CD8A, CDC20, E2F1, IL10, TNF, VCAM1) were overexpressed in GS 10 tumors, reflecting key pathways in tumor progression." (PMID 40227503, 2025). "Oxygenation facilitates the expression of adhesion molecules like ICAM-1 and VCAM-1 on endothelial cells, enabling effective interactions between T cells and the tumor vasculature." (PMID 41048631, 2025). "VCAM-1 facilitated the influx of immune cells into the tumor site, potentially orchestrating an immune response to promote or inhibit tumor progression, depending on the context and specific immune cell subsets involved." (PMID 40927361, 2025). "The adhesion molecules VCAM1 and ICAM1 guide immune cell transmigration, with ICAM1 favoring neutrophils, macrophages, and lymphocytes, while VCAM1 primarily recruits monocytes and lymphocytes, ultimately regulating the tumor immune microenvironment." (PMID 40652770, 2025). "Compared with the VCAM1– tumor cells from the primary tumor xenograft (CTC-205), VCAM1+ tumor cells sorted from the lung metastases (CTC-205-Met-VCAM1) promoted heterotypic clustering with WT Jurkat cells." (PMID 40955669, 2025). "Given the role of the vascular cell adhesion molecule 1 (VCAM1) in neutrophil infiltration (53, –55), we performed a Western blot for VCAM1 in tumor tissue lysates (n = 3 mice per group)." (PMID 40953263, 2025). "Soluble VCAM-1 also modulates gemcitabine resistance in PC by attracting macrophages to the tumour microenvironment." (PMID 41228228, 2025). "Elevated VCAM-1 and ICAM-1 levels in tumor tissue were strongly associated with increased cancer recurrence risk, suggesting their involvement in metastasis and immune evasion." (PMID 40652770, 2025). "Upregulation of VCAM-1 in the vessels following cerebrovascular inflammation promoted the interaction of circulating tumor cells with endothelial cells and thus their extravasation." (PMID 40071851, 2025). "Studies have shown that macrophage-membrane-coated nanoparticles can achieve specific accumulation of tumor tissue through receptor-mediated interactions such as VCAM-1." (PMID 41155938, 2025).
tumor (continued). "Specifically, both unpaired and paired differential expression analyses of the normal and GC cohorts revealed significantly higher VCAM-1 levels in the tumor tissues than in the normal tissues." (PMID 40927361, 2025). "Melanoma-derived EVs transfer tumor antigens to draining LNs mediated by VCAM-1 signaling, and interact with LN-resident LECs and medullary sinus macrophages, contributing to pathological LN remodeling, pre-metastatic niche formation, and immune inhibition." (PMID 41511312, 2025). "Adenosine reduces the expression of T-cell adhesion molecules (e.g., ICAM-1, VCAM-1), limiting the homing of effector T cells to tumor tissue while inhibiting the antitumor activity of NK cells and macrophages." (PMID 41415289, 2025). "Mechanistically, the integrin heterodimer α4β1, also named very late antigen 4 (VLA-4), in DPT cells and its ligand, VCAM1, in tumor cells are essential mediators of DPT-CTC clusters." (PMID 40955669, 2025). "An upregulation of ICAM-1 and VCAM-1 in the tumor following treatment appeared to be responsible for this phenotype." (PMID 40071851, 2025). "In tumor tissues, both VCAM-1 and ICAM-1 levels were significantly elevated in the recurrence group." (PMID 40652770, 2025). "Macrophage-membrane-coated SPIONs bearing PSGL-1 and VLA-4 can recognize VCAM-1 upregulated around tumor vessels, facilitating receptor-mediated transport across the ABB while avoiding healthy segments." (PMID 41155938, 2025). "VCAM-1 interacts with integrin VLA-4 in monocytes and tumor-associated macrophages, recruiting it to the lung tissues." (PMID 40927361, 2025). "Further, the underdeveloped vasculature of GBM can hinder CAR-T-cell extravasation into tumor tissue by downregulating vascular cell adhesion molecule 1 (VCAM1)." (PMID 38727262, 2024). "To understand the mechanisms by which tumor VCAM1 controlled behavior of intratumoral iNKT cells, we sorted iNKT cells from Vcam1 knockdown MC38 tumors and NTC MC38 tumors and compared their transcriptomes." (PMID 38332012, 2024). "The combination of ipilimumab and bevacizumab induces the expression of E-selectin, ICAM-1, and VCAM-1 on tumor endothelial cells and the adhesion of activated T cells to tumor endothelial cells." (PMID 39325128, 2024). "Studies have shown that overexpression of VCAM1 can enhance tumor invasion and migration and promote tumor metastasis." (PMID 38516703, 2024). "Knockdown of Vcam1 in tumor cells led to different gene expression patterns in intratumoral iNKT cells, with 267 genes were upregulated and 291 genes were downregulated." (PMID 38332012, 2024). "H. pylori infection increases vascular adhesion molecule 1 (VCAM1) levels in CAFs, and VCAM1 subsequently promotes tumour invasion via interaction with integrin αvβ5 on the tumour cell surface." (PMID 38862740, 2024). "Previous studies have demonstrated that exosomal miRNAs released by tumor cells have a significant influence on vasculature remodeling via IL-8-activated VCAM-1." (PMID 39187523, 2024). "Dual angiopoietin-2 (Ang-2) and VEGF blockade induce a higher expression of VCAM-1 on tumor endothelial cells, allowing the accumulation of antitumor T cells." (PMID 39325128, 2024). "One proposed mechanism involves the production of IL-6 by cancer-associated fibroblasts (CAFs), which subsequently upregulates the expression of VCAM-1 on the surface of tumor cells." (PMID 39596815, 2024). "In line with our results that knockdown of Vcam1 in MC38-mCherry tumor cells enhanced iNKT cell infiltration into tumors and augmented their IFN-γ production, knockdown of tumor Vcam1 further enhanced anti-tumor efficacy of iNKT cells." (PMID 38332012, 2024). "Apigenin exhibits anti-angiogenic properties by inhibiting the angiogenic factors such as VEGF, SPOCK 1, VCAM-1 thereby impeding the establishment of secondary tumor sites." (PMID 38515580, 2024). "Together, our data indicate that tumor VCAM1 inhibits iNKT cell motility and activation via reducing CDC42 expression." (PMID 38332012, 2024).